KLF2 (KLF transcription factor 2)
Diseases named in the same sentence as KLF2 in open-access papers (continued):
Sharing a sentence is not in itself a finding about the gene and the disease.
atherosclerosis (continued). "In addition, KLF2 has been shown to regulate the expression of genes involved in lipid metabolism and transport, which are important for the development of atherosclerosis." (PMID 36984888, 2023). "Thus, KLF2 has a role in protecting the endothelium from inflammation and damaging factors, which plays an important role in preventing atherosclerosis." (PMID 36984888, 2023). "According to recent evidence, EVs produced by KLF2-modified ECs (KLF2-EVs) attenuate disease progression, especially in subjects with pulmonary hypertension, atherosclerosis, myocardial ischaemia–reperfusion (I/R) injury and other diseases associated with vascular remodelling." (PMID 35139878, 2022). "Herein, we present a comprehensive overview of the role of KLF2 in atherosclerosis and as a pharmacological target for different drugs and natural compounds and highlight the potential application of these phytochemicals for the treatment of atherosclerosis." (PMID 35203463, 2022). "Artesunate, a derivative of plant-extracted malaria drug artemisinin, was shown to reduce the formation of atherosclerotic plaques, acting through increased expression of KLF2 and LPL (lipoprotein lipase)—the central triglyceride hydrolyzing enzyme, which deficiency leads to atherosclerosis." (PMID 35203463, 2022). "Thus, suggesting the role of shear stress in down-regulation of ECs’ Foxp1 (via KLF2 repression) and inflammasome activation, promoting atherosclerosis." (PMID 35203463, 2022). "Furthermore, KLF2-overexpressed exosomes derived from EC prevented atherosclerosis by increasing the levels of atheroprotective miR-143 and miR-145." (PMID 35055187, 2022). "Another interesting finding connects KLF2 function in macrophages to atherosclerosis." (PMID 34696279, 2021). "Additionally, endothelial exosomes have been proven to play a role in the prevention of atherosclerosis through the Krüppel-like factor 2 (KLF2)-miR-143/145 pathway." (PMID 33572486, 2021). "KLF2 is known to be upregulated in response to shear stress and to induce activation of numerous downstream signaling pathways that exert protective effects against atherosclerosis." (PMID 33875621, 2021). "Previous studies showed that KLF2-transduced ECs could exert anti-inflammatory effect and mediate monocyte/macrophage (Mo/Mø) polarization in atherosclerosis 13, indicating that KLF2-modified ECs could be used for the treatment of inflammatory diseases." (PMID 33052233, 2020). "The analyses considered Kruppel-like factor 2 (KLF2) as a potential target of miR-25, because it has been identified in other cell lines in previous studies and is associated with protection against atherosclerosis." (PMID 31750260, 2019). "Furthermore, ECs overexpressing KLF2 secrete atheroprotective miRs-143/145 in microvesicles that reduce atherosclerosis by targeting genes critical for VSMC dedifferentiation (Mmp3, Elk1, Camk2d)." (PMID 29459900, 2018). "Collectively, our findings not only identified TA as a novel KLF2 activator but also demonstrated that KLF2 could serve as a promising therapeutic target for the treatment of atherosclerosis." (PMID 28751752, 2017). "Enhancing KLF2 expression and activity improves endothelial function and prevents atherosclerosis." (PMID 28751752, 2017). "Increasing KLF2 level could be helpful in increasing protective functional interest in potential treatment for atherosclerosis." (PMID 29125549, 2017). "Any factors or molecules, which could stabilize KLF2 protein level, would be promising for treatment of inflammatory diseases (such as RA, atherosclerosis, sepsis, etc.)and also in the expansion of T-reg populations (for treatment of autoimmune diseases)." (PMID 29125549, 2017). "In silico analysis of gene expression profiles from studies that assessed the effects of KLF2 overexpression in vitro and atherosclerosis in vivo on endothelial cells, identifies AQP1 as KLF2 downstream gene with elevated expression in the plaque-free vessel wall." (PMID 26717516, 2015).
atherosclerosis (continued). "Yet, aquaporin-1 signals observed in endothelium overlying macrophage-poor plaques suggest that expression of KLF2 occurs even in advanced stages of atherosclerosis, provided that the balance between local inflammatory burden and local shear stress is in favour of the latter." (PMID 26717516, 2015). "Furthermore, a role for miR-92a-dependent regulation of KLF2/KLF4 in the pathogenesis of atherosclerosis was recently demonstrated." (PMID 25540650, 2014). "Data showed that rapamycin induced the expression and activity of KLF2 at the statement of atherosclerosis and stents implantation, and may partly prevent stent thrombosis induced by DESs." (PMID 22937032, 2012). "However, the precise mechanism by which KLF2/4 regulates EC metabolism in atherosclerosis progression remains unclear." (PMID 40890841, 2025). "The activator of KLF2 presented anti-inflammatory effects and attenuated the adhesion of monocytes to endothelial cells, which could be a promising therapeutic strategy for atherosclerosis." (PMID 36291566, 2022). "Therefore, discovery of new small molecule compounds that are KLF2 activators may provide new therapeutic strategies for atherosclerosis." (PMID 36362263, 2022). "Therefore, extracellular vesicles derived from KLF2-overexpressing HUVECs may have a therapeutic effect on atherosclerosis through the functions of miR-143 and miR-145." (PMID 35055187, 2022). "Thus, modulating KLF2 expression or activity could be a new therapeutic strategy for inflammatory-related disease such as atherosclerosis." (PMID 28751752, 2017). "Therefore, the possibility should be considered that KLF2 exerts atheroprotective effects in the endothelium beyond the onset of atherosclerosis and may thus contribute to plaque stabilization." (PMID 26717516, 2015). "In contrast, at sites of disturbed flow, where endothelial cells do not express KLF2, Ang2 can be released from the WPBs, promoting inflammation and vascular remodeling and therefore making these sites more susceptible to premature atherosclerosis and plaque neovascularization." (PMID 22715381, 2012). "For example, both KLF2 and KLF4 members can protect ECs, which exerts a beneficial effect on atherosclerosis." (PMID 41373858, 2025). "OS reduces the activity of shear-responsive regulators (KLF2 and KLF4), promotes glycolysis, and inhibits mitochondrial respiration, contributing to EC dysfunction and atherosclerosis." (PMID 40890841, 2025). "Similar to KLF2, KLF4 exerts protective effects in atherosclerosis through EC protection, inflammation modulation, and PCD regulation." (PMID 41373858, 2025). "S-flow activates KLF2 and KLF4, transcription factors critical for suppressing atherosclerosis by modulating endothelial nitric oxide synthase (eNOS)-associated pathways, including cGMP-PKG, cAMP, and insulin signaling." (PMID 41373858, 2025). "The protective effects of KLF2 and KLF4 in atherosclerosis make them an attractive target for the development of new treatments for cardiovascular diseases." (PMID 36984888, 2023). "Previous studies have revealed that KLF2 and KLF4 have an anti-inflammation function, which thereby protects aortic vessels from atherosclerosis." (PMID 35883633, 2022). "KLF2 (Kruppel like Factor 2) is the best-characterised member of the KLF family and mechanosensitive transcription factors with well-studied roles in atherosclerosis." (PMID 36232962, 2022). "In total, emerging evidence indicates that endothelial KLF2 is the major MSTF that regulates vascular homeostasis EC metabolism and represents a promising therapeutic target for atherosclerosis treatment and prevention by pharmacological intervention." (PMID 35203463, 2022). "Krüppel-like factor 2 (KLF2), 5-hydroxytryptamine transporter (5-HTT) inhibitor, miR-33a-5p antagomir, and miR-221 agomir are the protective factors of atherosclerosis." (PMID 35620296, 2022).
atherosclerosis (continued). "Laminar blood flow was found to induce KLF2 and KLF4 expression in the vascular endothelium, whereas KLF2 and KLF4 expression is reduced in areas of impaired blood flow as well as in areas prone to atherosclerosis." (PMID 36077168, 2022). "Expression of KLF2 by endothelial cells is known to exert protective effects against atherosclerosis, however OSS greatly reduces expression of KLF2 at both the mRNA and protein levels." (PMID 33875621, 2021). "By searching miRs target gene predicting database and available published reference, we found 17 potential miR-92a target genes related to vascular inflammation and atherosclerosis and only 3 with anti-atherogenic properties, which are RGS3, KLF2 and GDF11." (PMID 29777114, 2018). "During atherosclerosis, RNCR3 is significantly upregulated, which alleviates miR-185-5p repression effect, thereby upregulating the level of miR-185-5p target gene, KLF2." (PMID 27253412, 2016). "Our data provide support for a continuous role of KLF2 in stabilizing the vessel wall via co-temporal expression of eNOS and AQP1 both preceding and during the pathogenesis of atherosclerosis." (PMID 26717516, 2015). "Here, we examined the role of KLF2 in regulation of AQP1 expression and studied expression of AQP1 mRNA and protein during the pathogenesis of atherosclerosis in human vascular tissue." (PMID 26717516, 2015). "Beyond KLF2 and KLF4, other KLF members contribute to atherosclerosis management." (PMID 41373858, 2025). "For example, the KLF-related drug metformin does not directly and accurately act on KLF2 to exert its anti-atherosclerosis effect." (PMID 41373858, 2025). "Upon activation induced by H2O2, P90RSK inhibits transcriptional activation of ERK5 and adjusts the subsequent expression of KLF2-eNOS and VCAM-1, thus inhibiting endothelial cells (ECs) inflammation and modulating the function of the ECs, which is responsible for atherosclerosis." (PMID 38606153, 2024). "While many immune pathways were enriched in the upregulated DEGs (e.g., CXCR5, IL21R, CCR7 and CD22) (A,C), pathways such as “lipid and atherosclerosis’ and “fluid shear stress and atherosclerosis” were enriched in the downregulated DEGs (such as NOS3, KLF2 and KLF4)." (PMID 37218991, 2023). "Thus, KLF2 and KLF4 play crucial roles in the molecular mechanisms of atherosclerosis, regulating multiple pathways involved in endothelial cell function and other vascular wall and blood flow cells, as well as in inflammation and lipid metabolism." (PMID 36984888, 2023). "The large family of KLFs in humans includes 18 members, among which KLF2 and KLF4 are at the crossroads between endothelial cell mechanobiology and immunometabolism, which play important roles in both the normal vascular wall and atherosclerosis." (PMID 36984888, 2023). "There are many key molecules involved in the laminar shear stress and atherosclerosis pathways, such as endothelin 1 (EDN1), vascular cell adhesion molecule 1 (VCAM1), KLF2, intercellular adhesion molecule 1 (ICAM1), and platelet and endothelial cell adhesion molecule 1 (PECAM1)." (PMID 36364780, 2022). "Since miR-155 acts as an atherosclerosis inducer, regulation of KLF2 and/or KLF5 expression in the vascular system may be important to prevent atherosclerosis." (PMID 35055187, 2022). "Consistent with a proposed role of ERK5, KLF2, and KLF4 in atheroprotection, various mouse models of atherosclerosis further established a key role of the ERK5/KLF2/KLF4 cascade as a flow-regulated signaling module that safeguards from atherosclerosis." (PMID 34299213, 2021). "KLF2 expression is characteristically high in atherosclerosis-resistant regions of the vasculature but nearly absent at branch points and other atheroprone vascular segments with evidence of inflammation and NF-κB activation." (PMID 34026871, 2021).
atherosclerosis (continued). "Similarly, aloperine treatment also reduced oxidized low-density lipoprotein, a marker of endothelial inflammation, and reduced MCP-1, VCAM-1, IL-6, and E-selection by reducing Kruppel-like factor 2 (KLF2) expression, suggesting the potential anti-atherosclerosis characteristics." (PMID 35310033, 2022). "Therefore, KLF2 and KLF5 could be considered as new therapeutic targets for atherosclerosis." (PMID 35055187, 2022). "Interestingly, downregulation of KLF2 in ST conditions also lead to higher expression of the pro-inflammatory EC-specific MIF, consistent with KLF2 operating as a homeostatic modulator of MIF expression in endothelial cells, intrinsically protective against atherosclerosis." (PMID 29403061, 2018). "Unlike KLF2 and KLF4, KLF5 aggravates atherosclerosis via non-coding RNAs networks, including miRNAs, lncRNAs, and circRNAs." (PMID 41373858, 2025).
endothelial dysfunction (36 papers, 2013 to 2025). In vascular diseases, endothelial dysfunction is a systemic pathological state of the endothelium (the inner lining of blood vessels) and can be broadly defined as an imbalance between vasodilating and vasoconstricting substances produced by (or acting on) the endothelium. "Elevated miR-92a levels can cause endothelial dysfunction by targeting genes such as Krüppel-like factor 2 (KLF2), KLF4, and sirtuin 1 (SIRT1)." (PMID 41425580, 2025). "On the other hand, genetic or pharmacological activation of KLF2 reversed multiple aspects of the induced endothelial dysfunction thus proposing KLF2 activation as a plausible strategy to improve COVID-19 associated endothelial dysfunction." (PMID 35409070, 2022). "The role of KLF2 in the endothelial dysfunction has been further underlined by the treatment of endothelial cells with KLF2 siRNA (siRNA against KLF2)." (PMID 35409070, 2022). "By virtue of the anti-thrombotic and anti-inflammatory properties mediated by KLF2 activation, these drugs/compounds have the potential to lower COVID-19-associated endothelial dysfunction and mortality." (PMID 34253708, 2021). "We next explored the underlying mechanism of KLF2 in restoring OGD-induced endothelial dysfunction." (PMID 36632224, 2023). "Our study provides the proof-of-concept that KLF2 activation could be a potential strategy to ameliorate COVID-19-associated endothelial dysfunction and endothelialitis." (PMID 34253708, 2021). "Since statins have reported benefits in cardiovascular outcome in COVID-19 patients and statins are potent pharmacological activators of KLF2,13,14 we postulated that KLF2 activation by statins could counteract COVID-19-associated endothelial dysfunction." (PMID 34253708, 2021). "Interestingly, incubation of HAoECs with spike protein caused reduced expression of transcription factor KLF2, and increased expression of the pro-coagulant, vWF, consistent with induction of endothelial dysfunction." (PMID 34935423, 2021). "Studies show that low-density lipoprotein (LDL) downregulates Krüppel-like factor 2 (KLF2) in endothelial cells through DNA and histone methylation, resulting in endothelial dysfunction and a hypercoagulable state." (PMID 40786181, 2025). "It has been reported that KLF2 levels were reduced in peripheral monocytes of patients with AS by about 30%, and enhancing KLF2 expression by specific activators mitigated endothelial dysfunction and AS through downregulation of proinflammatory genes." (PMID 39092773, 2024). "Among the identified TFs, according to the literature, KLF2 has been evaluated as a therapeutic target for COVID-19-induced endothelial dysfunction." (PMID 37243274, 2023). "Taken together, these findings reveal that KLF2 overexpression alleviates OGD-induced endothelial dysfunction by modulating autophagy flux in SCI." (PMID 36632224, 2023). "The expression of Krüppel-like factor 2 (KLF2) activated by resveratrol or statins in LSECs repairs endothelial dysfunction while deactivating HSCs." (PMID 37063264, 2023). "Synthetic hBD-3 alone was sufficient to induce endothelial dysfunction as indicated by significantly reduced phospho-eNOS and KLF-2 expression." (PMID 35355507, 2022). "In contrast, KLF2 expression is reduced by disturbed stress in branched points of blood vessels with atheroprone flow patterns, resulting in endothelial dysfunction." (PMID 35269384, 2022). "This includes improvement in endothelial dysfunction through effects on Kruppel-like factor 2 (KLF-2) and increased nitric oxide (NO) bioavailability through modulation of endothelial NO synthase and enhancing eNOS mRNA stability." (PMID 36300180, 2022). "For these reasons KLF2 is emerging as an important factor in COVID-19-induced endothelial dysfunction and vascular disease and thus as a promising target for therapeutic intervention." (PMID 35409070, 2022).